GAS5 (growth arrest specific 5)
Diseases named in the same sentence as GAS5 in open-access papers (continued):
Sharing a sentence is not in itself a finding about the gene and the disease.
glioma (continued). "For instance, GAS5 inhibited the proliferation, migration and invasion of human glioma cells in vitro and in mice via promoting tumor suppressor Bcl-2-modifying factor (bmf) and Plexin C1 expression." (PMID 29225772, 2017). "Recent studies have reported that GAS5 negatively regulates the growth of cancer cell lines in vitro and in vivo, including gliomas." (PMID 28293170, 2017). "The induction of GAS5 is apparently detected during DOX-induced apoptosis in human glioma cell lines." (PMID 28293170, 2017). "For example, lncRNAs, such as HOTAIR, CRNDE, GAS5 and other lncRNAs with abnormal expression in glioma tissues and cell lines, regulate the biological behaviors of glioma cells." (PMID 29132362, 2017). "Gas5 suppresses the malignant biological characteristics by down-regulating miR-222 in human glioma." (PMID 27267902, 2016). "For example, lncRNA GAS5 can function as a ceRNA for miR-21; long non-coding RNA H19 promotes glioma cell invasion by deriving miR-675; Long non-coding RNA MEG3 functions as a competing endogenous RNA of miR-181 s to regulate gastric cancer progression." (PMID 27620004, 2016). "A recent study has revealed that erlotinib, a tyrosine kinase inhibitor that acts on the epidermal growth factor receptor, can significantly affect the expression of the GAS5 gene in glioma cells." (PMID 25925741, 2015). "In addition, IGF2BP2 induces chemoresistance in glioblastoma cells and lncRNA GAS5 represses gliomas stemness and malignancy." (PMID 39417309, 2025). "GAS5-induced apoptosis and reduced motility are reversed by miR-10b-5p overexpression, further demonstrating the oncogenic role of miR-10b-5p in sustaining glioma growth and invasion." (PMID 39796267, 2025). "Additionally, the long non-coding RNA GAS5 inhibits glioma progression by suppressing miR-10b-5p, indirectly affecting the Sirt1/PTEN/PI3K/AKT and MEK/ERK pathways." (PMID 39796267, 2025). "Moreover, GAS5 interacts with miR-18a-5p to promote glioma growth via a mimic mechanism that ultimately leads to metastasis." (PMID 37245177, 2023). "Glioma as another neural condition shows severe GAS5 downregulation compared to normal glial cells." (PMID 37620425, 2023). "Furthermore, due to the regulatory nature of lncRNAs, GAS5 was shown to be able to bind to GSTM3 in glioma cells." (PMID 37047296, 2023). "In the glioma, it was also shown that the levels of the SNORD44 and the Growth Arrest Specific transcript 5 gene (GAS5) were abnormally downregulated in a significant positive correlation in the glioma tissues and cells, which also correlated with the WHO grade." (PMID 36012529, 2022). "The current study revealed that GAS5 suppressed glioma cell growth, both in vitro and in vivo." (PMID 36106122, 2022). "This conclusion could be used to supplement our understanding of how GAS5 acts as a ceRNA in gliomas." (PMID 36106122, 2022). "qRT-PCR showed that GAS5 expression considerably decreased in glioma cells." (PMID 36106122, 2022). "In this study, we also found that downregulation of GAS5 in glioma could predict poor survival, and GAS5 overexpression could facilitate the migration and invasion of GBM cells and decrease cell viability and the antitumor effect of GAS5 in nude mice." (PMID 36106122, 2022). "Transwell assays revealed that GAS5 overexpression suppressed the invasive ability of glioma cells." (PMID 36106122, 2022). "Emerging evidence has indicated that GAS5 and other lncRNAs could sponge miRNAs to repress their expression and further suppress their downstream pathways, either in glioma or other cancers." (PMID 36106122, 2022). "GAS5 negatively regulates the malignant behavior of glioma cells and GSCs." (PMID 36106122, 2022). "In summary, GAS5 exerts a tumor suppressive effect in glioma through interactions with miRNAs." (PMID 33391419, 2021). "GAS5 may be a biomarker for diagnosis and prognosis, and even a potential target for glioma treatment, and therefore warrants further investigation." (PMID 33391419, 2021).
glioma (continued). "Low-grade glioma patients with high GAS5 expression had a higher probability of survival." (PMID 33391419, 2021). "Recently, studies have shown that GAS5 is a potential therapeutic target in glioma, and may be related to chemotherapy resistance during treatment." (PMID 33391419, 2021). "GAS5 by suppressing excessive autophagy in an mTOR‐dependent manner could facilitate glioma cell sensitivity to cisplatin." (PMID 34178658, 2021). "Second to MEG3, the anti-tumoral effects of GAS5 are well investigated in glioma." (PMID 34322395, 2021). "In this review, we describe the roles and mechanisms of GAS5 in glioma." (PMID 33391419, 2021). "GAS5 levels could effectively predict the survival rates of low-grade glioma, including grades II and III." (PMID 33391419, 2021). "Several reports have suggested that GAS5 may be a target for treatment of glioma, involved in overcoming drug resistance, and for increasing chemosensitivity in other cancers." (PMID 33391419, 2021). "Recently, the role of GAS5 has also been reported in the pathology of glioma." (PMID 33391419, 2021). "miRNAs, key players in the pathogenesis of glioma, are essential targets of GAS5." (PMID 33391419, 2021). "Taken together, these results indicate that GAS5 could improve the sensitivity of glioma tumor cells to chemotherapy, thereby enhancing the effectiveness of treatment." (PMID 33391419, 2021). "However, understanding the mechanism of action of GAS5 in the pathogenesis of glioma requires further research." (PMID 33391419, 2021). "In this study, we focused on GAS5, one crucial noncoding gene in glioma progression." (PMID 30853980, 2019). "In addition, grade II, grade III, and grade IV gliomas had similar expression levels of GAS5, which were all higher than that of normal brain tissues." (PMID 30853980, 2019). "The expression of the lncRNA growth arrest–specific 5 (GAS5) is downregulated in glioma tissues." (PMID 29618386, 2018). "In addition, both Plexin C1 and its positive regulator GAS5, a long non-coding RNA, were downregulated in glioma tissues and cell lines." (PMID 30327758, 2018). "GAS5 inhibits the migration and invasion of U87 and U251 human glioma cell lines." (PMID 29618386, 2018). "GAS5 suppresses the malignancy of human glioma stem cells via a miR-196a-5p/FOXO1 feedback loop." (PMID 29552296, 2018). "Elevated levels of GAS5 decreased the expression of miR-222 through directly targeting in glioma cells; meanwhile, tumor suppressor Bcl-2-modifying factor (bmf), as the downstream target of miR-222, was up-regulated, and thus inhibited glioma cell proliferation." (PMID 29225772, 2017). "LncRNA Gas5 inhibits carcinogenesis in human glioma by targeting miR-222." (PMID 29212233, 2017). "For instance, GAS5 inhibits the growth of melanoma cells by promoting miR-137 transcription, and its upregulation suppresses cell proliferation and promotes apoptosis of human glioma cells by inhibiting miR-222 expression." (PMID 29029523, 2017). "GAS5 may blunt the resistance of glioma cells to cisplatin by suppressing excessive autophagy through the activation of mTOR signaling, implying a promising therapeutic strategy against chemoresistance in glioma." (PMID 36245971, 2022). "Although GAS5 has been shown to regulate glioma cells, its detailed mechanisms remain unclear." (PMID 36106122, 2022). "Moreover, our study was the first to show that GAS5 can affect the stemness of glioma cells." (PMID 36106122, 2022). "Furthermore, GAS5 was found to inhibit excessive autophagy in glioma." (PMID 34322395, 2021). "In addition, the overexpression of GAS5 could enhance the cellular response to erlotinib, a tyrosine kinase inhibitor used as a second line treatment for glioma." (PMID 28293170, 2017).
glioma (continued). "To determine whether the increase of SNORD76 following the HOTAIR siRNA-expressing lentivirus treatment was coincidental, we used quantitative PCR to evaluate the expression of HOTAIR, SNORD76, and GAS5 in 5 glioma cell lines (U87, U87-EGFRvIII, LN229, U251 and SNB19)." (PMID 25715874, 2015). "The GAS5/miR-222 axis has been suggested to inhibit the BCL-2-modifying factor (BMF) and its downstream BAX protein, thereby delaying the proliferation of glioma cells." (PMID 39941145, 2025). "GAS5 overexpression lowered cell viability, suppressed GBM cell migration and invasion, and impaired the stemness and proliferation of glioma stem cells (GSCs)." (PMID 36106122, 2022). "To further investigate this correlation, we evaluated the clinical data of 72 patients and found that the pathological grading of glioma and the KPS score of patients significantly correlated with GAS5 expression." (PMID 36106122, 2022). "Expression of many lncRNAs has been shown to be dysregulated in glioma, such as the up-regulation of NEAT1, HOTAIR, FOXM1-AS, H19, SOX2OT, and HCP5 expression and the down-regulation of GAS5, NBAT-1, and CASC2 expression." (PMID 35359381, 2022). "For example, GAS5 and HOTAIR were dysregulated in gliomas and related to the proliferation, migration, invasion and chemosensitivity of glioma cells 28, 35-37." (PMID 34659533, 2021). "The genes most strongly related to GAS5 were analysed in the TCGA dataset and validated with a CGGA (Chinese Glioma Genome Atlas) dataset." (PMID 30853980, 2019). "Via bioinformatic analysis based on TCGA-LGG and TCGA-GBM data, we explored the mechanisms of GAS5 expression in LGG (grades II and III) and high-grade glioma (glioblastoma multiforme, grade IV)." (PMID 30853980, 2019). "In addition, another study suggested that GAS5, miR-196a-5p, and Forkhead Box Protein O1 (FOXO1) form a positive feedback loop in glioma stem cells." (PMID 39941145, 2025). "Studies have shown that TUG1 and MEG3 expression levels are reduced in human glioma tissues, with TUG1 promoting cell apoptosis and suppressing proliferation, migration, and invasion, while GAS5 was identified as a suppressor that enhances glioma therapy efficacy by directly targeting miR-222." (PMID 40004468, 2025). "Moreover, the GAS5/miR-196 axis increases the level of phosphotyrosine interaction domain containing 1 (PID1) protein, thus inhibiting glioma stem cell tumorigenicity and growth." (PMID 39941145, 2025). "GAS5 lncRNA targets GSTM3, so it is expressed in glioma cells compared to glial cells." (PMID 37620425, 2023). "Further analysis indicated that overexpression of GAS5 in GSCs substantially diminished the expression of stem cell markers, including CD133 and Notch1, which are related to the stemness and malignant progression of gliomas." (PMID 36106122, 2022). "LncRNA PART1 can suppress glioma proliferation and migration via miR-374b/SALL1 axis, LINC00689 can inhibit glioma tumorigenesis via the miR-526b-3p/IGF2BP1 axis, GAS5 can alter the EMT process, proliferation, migration, and invasion of glioma cells through miR-106b targeting PTEN." (PMID 36425564, 2022). "As indicated by flow cytometry assays, elevated GAS5 levels suppressed the apoptosis of glioma cells, but knockdown of GAS5 did not have an obvious influence on cell apoptosis." (PMID 36106122, 2022). "GAS5 is not a specific predictor of glioma, but can be used to predict the prognosis for glioma after excluding other diseases, or by combining it with other predictors." (PMID 33391419, 2021). "Similar to GAS5, SNORD44 was expressed at low levels in glioma cells." (PMID 33391419, 2021). "In this regard, recent studies have demonstrated that lncRNAs in gliomas can serve as molecular decoys, which move proteins or RNAs away from a specific location, like a “sponge” to miRNAs (e.g., HOTAIR/miR-326, CASC2/miR-21, XIST/miR-152, and Gas5/miR-222)." (PMID 28293170, 2017).
glioma (continued). "Furthermore, we examined the expression of SNORD47, GAS5, HOTAIR in 124 clinical glioma specimens of different grades: WHO grade I/II (n=40), grade III (n=48), and grade IV (n=36)." (PMID 28410200, 2017). "Moreover, with an increase in glioma grade, the expression of GAS5 declined drastically, indicating a latent negative relationship between the expression level of GAS5 and glioma grade." (PMID 36106122, 2022). "Another study in glioma stem cells showed that GAS5 can also upregulate the other member of the FOXO family, namely FOXO1 via downregulating miR-196a-5p expression resulting in inhibition of cell proliferation, migration, invasion, and promotes apoptosis in glioma stem cells." (PMID 35736636, 2022). "Many lncRNAs could regulate the progression of glioma, like NEAT1, HOTAIR, and GAS5." (PMID 34056009, 2021). "However, the potential roles of GAS5 involvement in gliomas and the regulatory mechanism of GAS5 expression in gliomas are not clearly identified." (PMID 30853980, 2019). "In summary, HOTAIR could regulate the expression of SNORD76 independent of regulation of the expression of GAS5, and SNORD76 caused marked repression of glioma growth in vitro and in vivo." (PMID 25715874, 2015). "However, 57.1% (32/56) of GAS5-mediated regulations are disease-specific, as illustrated by the finding that GAS5 regulates cell proliferation, cell migration, and cell invasion by sponging miR-18a-5p in glioma but sponging miR-196a-5p in triple-receptor negative breast cancer." (PMID 31713618, 2020).
lung carcinoma (70 papers, 2015 to 2025). "Key lncRNAs such as NEAT1, TUG1, MALAT1, HOTAIR, and GAS5 demonstrate a crucial role in lung cancer progression and serve as powerful prognostic and diagnostic biomarkers." (PMID 39201688, 2024). "The lncRNAs NNT Antisense RNA 1 (NNT-AS1) and growth arrest-specific 5 (GAS5) can also contribute to the increased risk for lung cancer in COPD patients." (PMID 36769181, 2023). "Contribution of GAS5 in the pathogenesis of lung cancer has been highlighted through the observed associations between genomic variants within this gene and risk of this malignancy." (PMID 30866866, 2019). "In lung cancer, only a small part of lncRNAs, such as H19, HOTAIR, MALAT1, ANRIL, and GAS5 have been identified to be tumor-associated especially in lung cancers." (PMID 30154938, 2018). "In current study, we found the del allele of GAS5 rs145204276 was significantly associated with decreased risk of lung cancer with a statistical power of 77%." (PMID 29207621, 2017). "The current study explored association between GAS5 rs145204276 and susceptibility of lung cancer using a case-control study in a Chinese population." (PMID 29207621, 2017). "Moreover, from this list, only H19, MALAT1, HOTAIR, and GAS5 were associated with exosomes and lung cancers in our PubMed search." (PMID 32438606, 2020). "Taken together, our findings provided strong evidence for the hypothesis that GAS5 rs145204276 were significantly associated with the susceptibility of lung cancer, and GAS5 functions as a tumor suppressor in carcinogenesis of lung cancer." (PMID 29207621, 2017). "Therefore, GAS5 is considered to be a potential diagnostic biomarker for lung cancer and a novel therapeutic target in patients with lung cancer." (PMID 26061969, 2015). "In addition, the GAS5 SNP rs145204276 is significantly correlated with lung cancer susceptibility." (PMID 36011604, 2022). "Besides which, lower GAS5 expression is associated with tumor angiogenesis in lung cancer." (PMID 35456391, 2022). "Recently, increasing evidence indicated that decreasing expression of GAS5 can affect the susceptibility of many kinds of cancers and associated with poorer prognosis of hepatocellular carcinoma, cervical cancer, renal cancer, lung cancer, gastric cancer and melanoma 24-26, 30-32." (PMID 31673232, 2019). "However, we found that GAS5 expression may be a more specific diagnostic biomarker of lung cancer, compared with other neoplasms." (PMID 29029523, 2017). "GAS5 acts as a tumor suppressor gene, and its expression is reduced in many lung cancer patients, negatively correlating with patient prognosis." (PMID 39991629, 2025). "GAS5, acting as a tumor suppressor gene, is expressed at reduced levels in many lung cancer patients and is negatively correlated with patient prognosis." (PMID 39991629, 2025). "For example, lncRNA GAS5 is a recently discovered as a tumor suppressor, which involves many cancers, such as breast cancer, prostate cancer, lung cancer, and colorectal cancer." (PMID 39705424, 2024). "The exosomes of lung cancer cells containing high GAS5 levels inhibited HUVECs proliferation and tube formation, increasing their apoptosis by sponging miR-29-3p and upregulating phosphatase and tensin homolog (PTEN) and inhibiting PI3K/AKT phosphorylation." (PMID 38392967, 2024). "In contrast, GAS5 was lowly expressed in human lung cancer tissues, lung cancer cells, and cell culture supernatant exosomes." (PMID 38392967, 2024). "EVs derived from lung cancer cells contained the lncRNA growth arrest-specific 5 (lncRNA GAS5), upregulating PTEN expression and inhibiting the PI3K/AKT phosphorylation, thereby increasing angiogenesis." (PMID 36671802, 2023). "GAS5 is expressed at low levels in human lung cancer tissues, lung cancer cells, and cell culture supernatant exosomes." (PMID 37151887, 2023).